NR4A1 (nuclear receptor subfamily 4 group A member 1)
Diseases named in the same sentence as NR4A1 in open-access papers (continued):
Sharing a sentence is not in itself a finding about the gene and the disease.
breast cancer (continued). "NR4A1 impacts both fatty acid synthesis and oxidation, providing a dual advantage of metabolic disruption and reduced tumor growth, presenting a promising strategy for cancers heavily reliant on lipid metabolism, such as breast cancer." (PMID 40427160, 2025). "Here we report the biological effect of NR4A1 in suppressing breast cancer (BC) growth." (PMID 40164686, 2025). "Researchers explored how NR4A1 affects breast cancer (BC) growth and metabolism." (PMID 40164686, 2025). "In previous studies, we have shown that the CDIM compounds inhibit the growth of multiple cancer cell lines and, in breast cancer cells, the knockdown of NR4A1 abrogated the growth inhibitory effects of DIM-3-Cl-5-OCH3, DIM-3-Cl-5-OCF3, DIM-3-Cl-5-CF3, and DIM-3-Br-5-OCF3." (PMID 38540704, 2024). "Additionally, CsnB also acts as a candidate to downregulate CD36/FABP4 expression, leading to the inhibition of fatty acid uptake and consequent breast cancer cell proliferation in NR4A1-dependent manner." (PMID 36052242, 2022). "Our study found that NR4A1, 2, and 3 gene expressions are luminal breast cancer-specific." (PMID 35547878, 2022). "PLEXIND1, on the other hand, has been reported to promote apoptosis in association with orphan nuclear receptor NR4A1 in the absence of Sema 3E in a breast cancer mouse model." (PMID 34439202, 2021). "Here, we demonstrated that NR4A1, whose expression was downregulated in TamR cells and patients with recurrent breast cancer treated with tamoxifen, may be a new prognostic factor and therapeutic target for tamoxifen resistance." (PMID 34209871, 2021). "This evidence raises the possibility that NR4A1 genes may contribute to the negative regulation of the ERK signaling pathway in breast cancer." (PMID 34209871, 2021). "Additionally, using an immune-histochemical analysis of tissue samples from 175 breast cancer patients, it was found that NR4A1 expression correlated with poor prognosis." (PMID 30213113, 2018). "Another study observed NR4A1 overexpression in breast tumors with high immune infiltration and poor prognosis and showed a promoting role of NR4A1 in the invasion and metastasis of breast cancer cells by activating TGFβ signaling." (PMID 28903348, 2017). "Notably, NR4A1 expression levels are elevated in breast cancer patients with high immune cell infiltration and levels correlate with poor prognosis." (PMID 26131976, 2015). "Analysis of the pathological data showed more prominent cytoplasmic staining levels in breast cancers and a negative association of NR4A1 with increasing degrees of histological grade among the infiltrating duct carcinomas, and hence invasive potential." (PMID 20642837, 2010). "Our data propose that nuclear NR4A1 may play a protective role against breast cancer metastasis as it acts to inhibit both normal and tumour cell migration." (PMID 20642837, 2010). "While five of these genes were confirmed to be deregulated in breast cancer, our attention became focused on the orphan nuclear receptor NR4A1 - which was further confirmed to be upregulated twofold or more compared with normal breast in 9 out of the 16 F19-negative samples tested by real-time PCR." (PMID 20642837, 2010). "Higher grade 3 breast cancers (that is, those with a potentially poorer prognosis and the greater likelihood of metastasis in due course) are less likely to contain demonstrable levels of NR4A1." (PMID 20642837, 2010). "Similarly, the role of NR4A1 in breast cancer has been controversial." (PMID 34209871, 2021). "However, the functional role and associated molecular mechanism of NR4A1 in tamoxifen-resistant breast cancer have not been elucidated." (PMID 34209871, 2021). "Nr4a1 might also be an interesting BH3-candidate for Bcl2a1 in breast cancer for similar reasons." (PMID 31825969, 2019). "Thus, NR4A1 induction/activation may reduce breast-cancer growth, although this beneficial effect may be counterbalanced by increased metastatic-spread." (PMID 26894976, 2016).
breast cancer (continued). "Whole-genome cDNA screening results showed that nuclear receptor NR4A1 is a strong activator of transforming growth factor-β (TGF-β) signaling, which can enhance the migration, invasion, and metastasis of breast cancer cells." (PMID 40666103, 2025). "MIDN interacted with NR4A1, EGR1, and PSMC1, and it was especially co-expressed in liver cancer, pancreatic cancer, urothelial cancer, breast cancer and melanoma." (PMID 40002690, 2025). "Cytosporone B (CsnB), an NR4A1 agonist, was shown to downregulate SREBP1 expression, leading to the inhibition of lipogenesis and subsequent suppression of tumor growth in breast cancer models." (PMID 40427160, 2025). "Based on the Human Protein Atlas (HPA) database, we found that MIDN, NR4A1, PSMC1, and EGR1 were all positively expressed in liver cancer, pancreatic cancer, urothelial cancer, breast cancer, and melanoma." (PMID 40002690, 2025). "According to the The Cancer Genome Atlas (TCGA) and Molecular Taxonomy of Breast Cancer International Consortium (METABRIC) databases, NR4A1 mRNA was significantly decreased in all subtypes of BC." (PMID 40164686, 2025). "In our previous study of transcriptome analysis of mammary tumors of PyMTSB2−/− mice, the expression levels of cancer immune modulated genes (ANXA3, CCL17, CXCL13, CXCR3, IFN-γ, NR4A1, and SEMA3a) were significantly changed." (PMID 38956496, 2024). "To assess the functionality of the MALAT1/NR4A1 axis, we transfected MCF7 breast cancer and PANC1 pancreatic adenocarcinoma cells with Gapmers to downregulate MALAT1 expression." (PMID 38791553, 2024). "In contrast to the post-translational regulation of PD-L1 by glycosylase inhibitors, our previous study showed that NR4A1 regulates expression of PD-L1 in breast cancer cell lines and CDIM/NR4A1 antagonists decrease expression of this gene." (PMID 37847301, 2023). "For example, the checkpoint gene PD-L1 is regulated by NR4A1 in breast cancer cells and treatment with CDIM/NR4A1 antagonists decreased PD-L1 and enhanced immune surveillance (increased CD8 + /CD4 + ratios) in syngeneic mouse breast cancer model." (PMID 37847301, 2023). "Gene of Ccl17, Cxcl13, Cxcr3, IFN-γ, and Sema3a, were significantly decreased while the Anxa3 and Nr4a1 were significantly upregulated in SB2−/−;PyMT mammary tumors." (PMID 35768767, 2022). "Modulating the expression levels of NR4A1, NR4A2, and NR4A3 can be a potential therapeutic approach for breast cancer." (PMID 35547878, 2022). "In this study, surprisingly, we found that NR4A1 is mainly located in the cytoplasm of both MCF7 and TamR breast cancer cells and promoted the expression of apoptosis-related molecules, including caspase-7, caspase-9, and PARP." (PMID 34209871, 2021). "With a genome-wide cDNA screen, it was identified that inflammation-induced NR4A1 (NR4A2 and NR4A3 also respond) is a critical factor for the activation of TGF-β/SMAD-mediated breast cancer cell migration, invasion, and metastasis in vitro and in vivo." (PMID 33634114, 2021). "Recent studies have shown that ectopic expression of NR4A1 promotes invasion and metastasis by activating TGF-β/SMAD signaling in breast cancer." (PMID 34209871, 2021). "The overall survival data showed that the prognosis of breast cancer patients was poorer when two genes (FOS and FOSB) were highly expressed or when four genes (JUN, GADD45B, NR4A1, and BTG2) showed low expression levels." (PMID 34457116, 2021). "In breast cancer, CD109, ID4, and ST8SIA1 are involved in the maintenance of stem cell phenotype, whereas NR4A1 promotes TGF-β-induced EMT and invasion." (PMID 32679794, 2020). "NR4A1 is a strong activator of TGF-β/SMAD signaling promoting TGF-β mediated EMT, the migration of breast cancer cells and invasion and metastasis in vitro and in vivo." (PMID 30213113, 2018).
breast cancer (continued). "Next, we used the previously established K14-Cre×p53F/F×BRCA1F/F mice as a basal-like breast cancer model and p53F/F×BRCA1F/F mice as a normal control to study NR4A1 expression changes during tumor growth and progression." (PMID 28903348, 2017). "Analysis of the Metabric dataset obtained from 1986 specimens also identified a significant decrease in NR4A1 mRNA expression in luminal A/B, HER2-positive and basal-like breast cancers when compared with normal breast tissues." (PMID 28903348, 2017). "The ERα-positive breast cancer cells T47D and MCF-7 expressed high NR4A1 protein, while only one of the four examined TNBC cell lines, HCC70, showed NR4A1 protein expression." (PMID 28903348, 2017). "Our data demonstrated that NR4A1 protein is expressed in T47D and MCF-7 cells, which are ERα-positive breast cancer cells, but is barely detected in three out of four TNBC cell lines including MDA-MB-231, BT549 and BT20 cells." (PMID 28903348, 2017). "The effect on EMT is consistent with the observation that inflammatory cytokines induce NR4A1 and enhance TGF-β-dependent breast-cancer cell-invasiveness in-vitro and in-vivo." (PMID 26894976, 2016). "NR4A1 belongs to the NR4A family of nuclear receptors, and is considered a mediator/regulator of cell survival and apoptosis in breast cancer cells; it is up-regulated in primary breast cancer compared with normal tissue." (PMID 24655368, 2014). "In inflammation and stress-induced diseases such as solid tumors NR4A1 is overexpressed and is a negative prognostic factor for lung, ovarian, colon and breast cancer patients." (PMID 40313760, 2025). "NR4A1, PSMC1, and EGR1 were selected as MIDN-interacted proteins, and these four molecules were co-expressed in pancreatic cancer, liver cancer, urothelial cancer, melanoma, and breast cancer." (PMID 40002690, 2025). "The results showed that the NR4A1 gene was specifically regulated by MALAT1 in MCF7 breast cancer cells but not in pancreatic ductal adenocarcinoma PANC1 cells." (PMID 38791553, 2024). "In breast cancer cells, TGF-β-induced p38 kinase activity can phosphorylate NR4A1 and TGF-β-induced β-catenin can transactivate NR4A1 expression via formation of β-catenin/TCF/LEF complex and its binding to NR4A1 promoter." (PMID 38531859, 2024). "By analyzing TCGA data, we identified a positive correlation between NR4A1 expression and NR4A1-downstream RE accessibility in breast cancer but not in pancreatic cancer." (PMID 38791553, 2024). "The orphan nuclear receptor 4A1 (NR4A1, Nur77) is overexpressed in lung, colon, liver and breast cancers and in rhabdomyosarcoma and is a negative prognostic factor for lung, breast and colon cancer patient survival." (PMID 37847301, 2023). "In addition, NR4A1 and NR4A2 mRNA expressions are lower in basal breast cancer when compared to other subtypes of breast cancer." (PMID 35547878, 2022). "NR4A1 has been found to bind to the NBRE or coactivator SWI/SNF complex response elements by NR4A2 or PPARγ, resulting in the change of fatty acid-related genes ACOX, CPT1M, FABP2, and FABP4 in melanoma and breast cancer." (PMID 36052242, 2022). "In this study, we selected four 3,5-disubstituted CDIM compounds which exhibited the lowest KD values for binding NR4A1 and investigated their activity as antagonists of NR4A1-regulated pro-oncogenic pathways/gene products in MDA-MB-231 and SKBR3 breast cancer cells." (PMID 34072371, 2021). "Nevertheless, the exact role of NR4A1 in tamoxifen resistance in breast cancer has not been elucidated." (PMID 34209871, 2021). "The up-regulation of NR4A1, detected in both ER-positive and negative breast cancer, was correlated with a decreased relapse-free survival in breast cancer." (PMID 32664456, 2020). "At the age of 4 months when K14-Cre×p53F/F×BRCA1F/F mice had not developed any mammary tumor (early stage), high-level NR4A1 protein was also detected in the mammary gland luminal and myoepithelial cells of these mice." (PMID 28903348, 2017).
breast cancer (continued). "NR4A1-agonists induce apoptosis in mammary-tumor cells, although NR4A1 apoptotic activity is not necessarily related to NR4A1 transcriptional activity." (PMID 26894976, 2016). "MCF-10A cells had no change in proliferation when overexpressing Nr4a1 and measurements across many breast cancer tumors found Nr4a1 expression to be inconsistent, suggesting that Nr4a1′s role in breast cancer may be tumor specific." (PMID 31683815, 2019). "Correlation analysis in the TCGA dataset showed a non-significant correlation between methylation and expression levels of NR4A1 and 2 and a non-significant inverse correlation between methylation and expression levels of NR4A3 in breast cancer patients." (PMID 35547878, 2022). "The expression levels of NR4A1 decreased in patients with recurred (tamoxifen-resistant) luminal A type breast cancer treated with tamoxifen therapy (GSE1378) and hormone therapy (METABRIC) compared to those in patients with non-recurred (tamoxifen-sensitive) luminal A type breast cancer." (PMID 34209871, 2021).
triple-negative breast carcinoma (340 papers, 2009 to 2026). An invasive breast carcinoma which is negative for expression of estrogen receptor (ER), progesterone receptor (PR), and human epidermal growth factor receptor 2 (HER2). "In this study, we aimed to define the expression profiles and specific role of NR4A1 in the highly malignant triple-negative breast cancer (TNBC), which still lacks available targeted therapies." (PMID 28903348, 2017). "NR4A1 also inhibits growth and metastasis in triple-negative breast cancer." (PMID 34209871, 2021). "Additionally, NR4A1 expression suppresses cancer growth and progression in triple-negative breast cancer (TNBC) in vitro and in vivo, showing its role as a tumor suppressor." (PMID 34209871, 2021). "In addition, NR4A1 protein expression is decreased in triple-negative breast cancer (TNBC), and overexpression of NR4A1 inhibited TNBC growth and invasiveness." (PMID 33172112, 2020). "In contrast, in triple negative breast cancer (TNBC) MDA-MB-231 cells, NR4A1 promotes tumor invasion and metastasis by activating transforming growth factor beta (TGF-R) signaling." (PMID 38791553, 2024). "This study is based on the hypothesis that orphan nuclear receptor 4A1 (NR4A1) and NR4A2 maintain low levels of ferroptosis in triple negative breast cancer (TNBC) cells and bis-indole derived (CDIM) compounds act as NR4A1/2 ligands that induce ferroptosis by enhancing CD71 expression." (PMID 41184246, 2025). "This study is based on the hypothesis that orphan nuclear receptor 4A1 (NR4A1) and NR4A2 maintain low levels of ferroptosis in triple negative breast cancer (TNBC) cells and that bis-indole derived (CDIM) compounds act as NR4A1/2 ligands that induce ferroptosis by enhancing CD71 expression." (PMID 40313760, 2025).
breast tumors (177 papers, 2004 to 2026). "A separate study investigating Nr4a1 expression in breast tumors similarly reported low Nr4a1 expression in higher grade and metastatic breast tumors." (PMID 29311806, 2017). "In our study, NR4A1 was first identified in the DTET as one of the transcription factors upregulated in primary breast tumours." (PMID 20642837, 2010). "NR4A1 has the ability to reduce the migration of breast tumour cells as well as the ability to reduce migration, to alter the adhesion to ECM and integrin cell surface expression of normal mammary epithelial cells." (PMID 20642837, 2010). "Immunohistochemistry on tissue microarrays was performed to check NR4A1 protein expression in breast tumours." (PMID 20642837, 2010). "It is therefore possible that NR4A1 acts as an antimigratory factor in breast tumours, and further studies should be conducted to understand the mechanisms involved." (PMID 20642837, 2010). "By comparing non-malignant MCF10 breast epithelial cells with TNBC MDA-MB-231 cells and circulating patient-derived breast tumor cells, NR4A1 was recently reported to modulate IEG expression through interaction with gene bodies and suppression of transcriptional elongation." (PMID 38791553, 2024). "Since NR4A1 appears to have an adverse effect on tumour cells, further studies will be conducted to determine whether NR4A1 actually regulates β4 integrin expression in breast tumour cells." (PMID 20642837, 2010). "In summary, our study has shown that NR4A1 expression is reduced in metastatic breast tumours." (PMID 20642837, 2010).
invasive breast carcinoma (88 papers, 2005 to 2026). A carcinoma that infiltrates the breast parenchyma. "The expression levels of the NR4A1 gene are significantly reduced in various cancer tissues such as bladder urothelial carcinoma, invasive breast cancer, and head and neck squamous cell carcinoma." (PMID 41031160, 2025).